KDR (kinase insert domain receptor)
Diseases named in the same sentence as KDR in open-access papers (continued):
Sharing a sentence is not in itself a finding about the gene and the disease.
serous ovarian cancer (6 papers, 2019 to 2025). "The array results were validated by monitoring the expression of KDR/VEGFR2, CCL20, and VIP, as a representative set of pro-tumorigenic genes in the high-grade serous ovarian carcinoma cell lines Kuramochi and OVCAR8." (PMID 34439877, 2021).
breast angiosarcoma (5 papers, 2022 to 2025). A malignant vascular neoplasm arising from the breast. "KDR mutations have been associated with cardiac and primary breast angiosarcomas, and in our cohort, KDR was present in 17 (23.3%) of breast angiosarcoma samples, supporting its role in this subtype." (PMID 41301029, 2025). "An in vitro study demonstrated that 10% of patients with primary and secondary breast angiosarcomas exhibit activating KDR gene mutations; based on their activity in vitro, VEGFR inhibitors could be studied in KDR-overexpressing radiation-associated breast angiosarcomas." (PMID 38791996, 2024). "NGS data may have an impact on therapeutic strategies as well: for instance, one of six (17%) of the radiation-associated breast angiosarcomas in our cohort featured the amplification of the KDR gene encoding the amplification of the VEGFR2 tyrosine kinase receptor." (PMID 38791996, 2024). "Similarly, KDR mutations have been linked to breast angiosarcoma but did not demonstrate significant co-occurrence with PI3K3CA (p = 0.246)." (PMID 41301029, 2025).
neovascular age-related macular degeneration (5 papers, 2009 to 2026). "Several studies found that the KDR and FLT1 genotypes may represent predictive determinants of efficacy in ranibizumab-treated neovascular age-related macular degeneration (nAMD) patients." (PMID 35893809, 2022).
oral squamous cell carcinoma (5 papers, 2019 to 2023). "This is the first study to demonstrate the role of KDR/VEGFR2 on the survival of oral squamous cell carcinoma." (PMID 37341071, 2023). "The methylation of KDR was also correlated with the development and progression of oral squamous cell carcinoma." (PMID 31956659, 2019).
pituitary adenomas (5 papers, 2016 to 2025). "After analyzing the haplotype associations with pituitary adenoma, we revealed that individuals carrying KDR rs2071559, and rs1870377 haplotype A‐A had increased odds of PA occurrence." (PMID 37803932, 2023). "CDK5 also enhances the migration and invasion of prolactin pituitary adenomas, predominantly by phosphorylation of kinase insert domain receptor (KDR, also known as VEGFR2) at S229." (PMID 37993880, 2023). "Our results indicate that CDK5 mediates cell invasion through phosphorylation on KDR Ser-229 and KDR pSer-229 is a potential biomarker for pituitary adenomas." (PMID 27438154, 2016). "In summary, our results illustrated that CDK5-mediated KDR phosphorylation controls prolactin pituitary adenoma progression and KDR pSer-229 serves as a potential prognostic biomarker for both noninvasive and invasive pituitary adenomas." (PMID 27438154, 2016). "KDR pSer-229 is upregulated in invasive pituitary adenomas and correlated with poor prognosis in patients with prolactin pituitary adenomas." (PMID 27438154, 2016). "Here, we have demonstrated that CDK5 phosphorylates KDR at Ser-229 in prolactin pituitary adenomas, a step that is required for normal cell surface expression of KDR in cell migration and invasion in vitro." (PMID 27438154, 2016). "To determine whether there is a direct interaction between CDK5 and KDR, we immunoprecipitated KDR from human pituitary adenoma lysates and probed with a CDK5-specific antibody." (PMID 27438154, 2016). "Therefore, KDR phosphorylation at Ser-229 may play a critical role in invasiveness and predicting poor prognosis of prolactin pituitary adenomas." (PMID 27438154, 2016). "Immunoprecipitation of KDR led to coprecipitation of a detectable amount of CDK5 in noninvasive pituitary adenomas, with more intensive signaling in invasive pituitary adenomas." (PMID 27438154, 2016).
rectal cancer (5 papers, 2014 to 2026). A primary or metastatic malignant neoplasm that affects the rectum. "In addition, four of the five observed GEIs on rectal cancer survival were with high animal protein intake including with the KDR gene, a VEGF receptor that mediates VEGF-A induced production of Nitric Oxide (NO) by endothelial cells." (PMID 28956832, 2017).
ulcer (5 papers, 2013 to 2023). "Thus, it can be hypothesized that wound healing requires early release of CD34+KDR+ cells from the bone marrow while the subsequent observed reduction could be associated with homing of these cells to the ulcer area." (PMID 24358275, 2013). "CD34+KDR+ cells were increased in DFU patients when compared to at risk of DFU patients and were reduced at the end of the study in patients who healed their ulcers." (PMID 24358275, 2013).
gastric ulcer (4 papers, 2013 to 2024). An ulcerated lesion in the mucosal surface of the stomach. "The molecular events in granulation tissue that contribute to the mechanisms of gastric ulcer healing include the activation of genes encoding bFGF, FGF-R1,2,4, VEGF, and flk-1/KDR; Ang 1 and Ang 2; Tie 2 receptor; COX-2; SRF; NGF; SDF-1; and BMD-EPC via the activation of PI3K/Akt pathway." (PMID 34440733, 2021).
Hypercholesterolemia (4 papers, 2018 to 2023). An increased concentration of cholesterol in the blood. "Higher plasma KDR levels were linked to increased risks of CRC, circulatory system diseases, and metabolic disorders, including disorders of lipid metabolism, hypercholesterolemia and hyperlipidemia." (PMID 38049731, 2023).
Impaired glucose tolerance (4 papers, 2017 to 2024). An abnormal resistance to glucose, i.e., a reduction in the ability to maintain glucose levels in the blood stream within normal limits following oral or intravenous administration of glucose. "From the trials that incorporated a MICON protocol, one trial reported a 23% increase on CD34+/KDR+ EPCs in a normal glucose tolerance group, while no changes were observed in the impaired glucose tolerance and T2DM groups." (PMID 35022875, 2022).
inflammatory skin disease (4 papers, 2016 to 2025). Inflammatory skin disorders covers a broad category that includes many conditions ranging in severity, from mild itching to grave medical health complications These disorders are common in people of all ages and races. "Targeting the KDR/GEF-H1/RhoA pathway may reduce keratinocyte inflammatory responses, providing benefits in inflammatory skin disease." (PMID 40746859, 2025).
kidney tumor (4 papers, 2011 to 2025). "No increased expression of VEGF or KDR was seen in other types of kidney tumors." (PMID 39000466, 2024).
lung disease (4 papers, 2021 to 2026). "KDR, as the primary receptor for vascular endothelial growth factor (VEGF), orchestrates VEGF‐intervened processes such as cell migration, proliferation, and angiogenesis, while also contributing to airway epithelial regeneration during lung disease." (PMID 41509196, 2026).
periodontitis (4 papers, 2019 to 2025). An acute or chronic inflammatory process that affects the tissues that surround and support the teeth. "The cross-sectional design does not allow for an analysis of the temporal association between CD133+/KDR+ levels and periodontitis that should be assessed only with a longitudinal observation." (PMID 31817862, 2019). "More specifically, the authors found lower levels of CD34+ and KDR+ in patients with moderate to severe periodontitis and an inverse association with high CRP levels and EPCs, supporting the evidence of a two-way relationship between periodontitis and CVD." (PMID 31817862, 2019). "In this regard, low serum CD133+/KDR+ levels during periodontitis appear to be linked with the possibility of developing future endothelial dysfunction and CVD risk." (PMID 31817862, 2019). "Moreover, all patients presented an increase in the CD133+/KDR+ EPC levels with an extended level of periodontitis and tooth loss." (PMID 31817862, 2019). "This cross-sectional study analyzed the association between CD133+/KDR+ levels and periodontitis." (PMID 31817862, 2019). "Machine learning models, combined with Gene Set Variation Analysis (GSVA), identified five key genes (RGS1, ACAT2, KDR, TUBB2A, TDO2) linked to periodontitis." (PMID 39935835, 2025). "This study demonstrated that patients with periodontitis presented significantly lower CD133+/KDR+ levels compared to HCs." (PMID 31817862, 2019). "In conclusion, the results of the present study suggest that low serum CD133+/KDR+ levels appear to be negatively correlated with periodontitis and with the periodontal health status." (PMID 31817862, 2019). "The aim of the present study was to investigate the association and impact of periodontitis and tooth loss on a subtype of endothelial progenitor cell (EPC) levels (CD133+/KDR+)." (PMID 31817862, 2019). "Patients in the periodontitis group presented significantly lower median values of CD133+/KDR+ levels (66.4 (45.5–269.6 cells/μL)) compared to patients in the healthy control (HC) group (79.7 (24.3–313.2 cells/μL), p < 0.001)." (PMID 31817862, 2019). "The results of the present study showed that patients with periodontitis presented a significantly lower median proportion of CD133+/KDR+ levels (p < 0.001) compared to healthy controls." (PMID 31817862, 2019). "Patients in the periodontitis group presented significantly lower CD133+/KDR+ levels (66.4 (45.5–269.6 cells/μL)) compared to the HC group (76.7 (24.3–313.2 cells/μL), p < 0.001)." (PMID 31817862, 2019). "Moreover, the presence of periodontitis appears as a condition that negatively influenced CD133+/KDR+ levels." (PMID 31817862, 2019). "Periodontitis may have negatively affected CD133+/KDR+ levels." (PMID 36824233, 2023). "The results of the univariate regression models highlighted that, in all enrolled patients (periodontitis and healthy controls), CD133+/KDR+ levels significantly influenced the number of teeth and mean sites with BOP positive (p < 0.001)." (PMID 31817862, 2019).
sarcoidosis (4 papers, 2009 to 2023). Sarcoidosis is a multisystemic disorder of unknown cause characterized by the formation of immune granulomas in involved organs. "Two of the SNPs in this genetic signature, namely rs1891467 near TGFB2 and rs7667298 near KDR, had been reported to be associated with an acute course of sarcoidosis before in a German cohort." (PMID 37621457, 2023). "TGFB2 and KDR variants were reported to be associated in a German cohort with an acute course of sarcoidosis and variants of TNFRSF1B are known to influence the response to anti-TNF therapy in sarcoidosis." (PMID 37621457, 2023).
tendinopathy (4 papers, 2016 to 2021). "KDR 1192 GA and GA + AA genotypes were associated with lower risk of tendinopathy (OR: 0.41, 95% CI: 0.19–0.88 and OR: 0.47, 95% CI: 0.23–0.98, respectively)." (PMID 27930691, 2016). "Haplotype distributions of VEGF and KDR in volleyball athletes and their association with tendinopathy risk." (PMID 27930691, 2016). "In conclusion, our findings provide evidence that the KDR SNPs were associated with development of tendinopathy in Brazilian volleyball athletes." (PMID 27930691, 2016). "Recently, our group investigated whether polymorphisms in VEGF and its receptor KDR genes could be correlated with susceptibility to tendinopathy." (PMID 30021560, 2018). "We described evidences that the polymorphisms in KDR might alter receptor activity, influence the angiogenic process and consequently contribute to inter-individual variation in the development of tendinopathy in volleyball athletes." (PMID 30021560, 2018). "Polymorphisms in KDR may alter receptor activity, influence the process of angiogenesis and consequently contribute to inter-individual variation in the development of tendinopathy in athletes." (PMID 27930691, 2016). "The present results provide evidence that the KDR polymorphisms were associated with development of tendinopathy, and can contribute to identify new therapeutic targets or personalized training programs to avoid tendinopathy development in athletes." (PMID 27930691, 2016). "The aim of the study was to investigate whether genetic variants in VEGF and KDR genes can be correlated with susceptibility of tendinopathy in volleyball athletes." (PMID 27930691, 2016). "Therefore, the present study aimed to explore VEGF and KDR SNPs as potential biomarkers for tendinopathy susceptibility among Brazilian volleyball athletes." (PMID 27930691, 2016). "Polymorphisms in VEGF and KDR may alter protein concentrations, influence the process of angiogenesis and consequently may contribute to inter-individual variation in the development of tendinopathy in athletes." (PMID 27930691, 2016). "After adjusted by age, years of practice in volleyball, gender and pain, there was negative risk association for the development of tendinopathy for the KDR CGA and CAT haplotypes, compared with the reference haplotype CGT." (PMID 27930691, 2016). "Association analyses of the KDR 1192G>A polymorphism in tendinopathy cases compared with athletes without disease." (PMID 27930691, 2016). "In the present study, we observed negative risk associations with the development of tendinopathy in athletes for the KDR 1192G>A SNP." (PMID 27930691, 2016). "The VEGF -2578C>A, -460T>C, +936C>T and KDR -604C>T, 1192G>A and 1719T>A SNPs were in HWE in the overall athletes study population and in each group (tendinopathy cases and controls)." (PMID 27930691, 2016).
unstable angina (4 papers, 2013 to 2021). "Levels of the CD45dimCD133+KDR+CXCR4+ EPCs subpopulation were also significantly reduced, at baseline, in patients who underwent unstable angina or MACE during the 2-year follow-up period." (PMID 24934236, 2014).
aortic stenosis (3 papers, 2012 to 2021). Aortic valve stenosis is a aortic valve disease caused by the incomplete opening of the aortic valve. "We aimed to assess the basal number of CD34+/KDR+ and CD34+/CD144+ cells in CABG patients, compared to aortic stenosis valvular replacement patients." (PMID 22214418, 2012). "Panel A, CABG and aortic stenosis valvular patients did not possess a significantly different level of CD34+/KDR+ cells, although a decreasing trend was noted for CABG." (PMID 22214418, 2012).
metastasis (3 papers, 2013 to 2020). The spread or migration of cancer cells from one part of the body (where they first appeared) to another. "For the KDR expression level, there was a significant difference between the patients with hepatic metastasis and the patients without hepatic metastasis (P= 0.02), while the co-expression level of VEGF and KDR in the patients with hepatic metastasis was significantly increased (P=0.005)." (PMID 23946799, 2013).
osteoarthritis (3 papers, 2015 to 2021). A noninflammatory degenerative joint disease occurring chiefly in older persons, characterized by degeneration of the articular cartilage, hypertrophy of bone at the margins and changes in the synovial membrane. "The presence of CD34+KDR+ cells was previously shown also in the synovial tissue of patients with RA and osteoarthritis, indicating that this is not a specific finding in JIA." (PMID 25925313, 2015).
rhabdomyosarcoma (3 papers, 2012 to 2024). A rare aggressive malignant mesenchymal neoplasm arising from skeletal muscle. "In contrast, EGFR (epidermal growth factor receptor), VEGFR2 (VEGF receptor 2 = KDR), and PDGFRA (platelet-derived growth factor receptor α) were overexpressed in embryonal, and ERBB3 (ErbB3) in alveolar and unclassified rhabdomyosarcomas." (PMID 23227212, 2012).
Tetralogy of Fallot (3 papers, 2020 to 2024). A congenital cardiac malformation comprising pulmonary stenosis, overriding aorta, ventricular septum defect, and right ventricular hypertrophy. "Rare genetic variants in KDR, encoding the vascular endothelial growth factor receptor 2 (VEGFR2), have been reported in patients with tetralogy of Fallot (TOF)." (PMID 34113005, 2021).
uveal melanoma (3 papers, 2016 to 2025). A melanoma derived from melanocytes of the uveal tract. "These uveal melanoma patients exhibit an increase in the expression of classic and well-documented hypoxia-dependent genes such as PDGFB, LOXL2, VEGF, ANGPT2, KDR, and S1PR1." (PMID 40000790, 2025).
vasculitis (3 papers, 2007 to 2021). "In contrast to adults with AAV, we have previously shown that children with active SV respond to endothelial injury by release of CD34 + CD133 + KDR+ EPCs into the circulation, possibly as an adaptive response to endothelial injury caused by vasculitis." (PMID 26475131, 2015). "This prevents the false inclusion of CD34 and KDR double-positive mature endothelial cells which, as a result of vasculitis, might have detached from the vascular wall." (PMID 17764548, 2007). "Previously, we demonstrated that children with active systemic vasculitis (SV) have higher circulating CD34 + CD133 + KDR+ endothelial progenitor cells (EPC); the function of these EPCs, and their relationship with disease activity in vasculitis remains largely unexplored." (PMID 26475131, 2015).
abortion (2 papers, 2015 to 2019). the ending of pregnancy by removing a fetus or embryo before it can survive outside the uterus. "Real-time PCR and Melting Analysis technique, Gln472His (A/T) polymorphism of the KDR gene were evaluated in study groups (50 abortion materials and 50 control subjects), and the results were compared between both the fetus and control groups." (PMID 31508572, 2019). "In the present study, the association between the KDR gene and the occurrence of idiopathic recurrent spontaneous abortion were studied using three tag SNPs." (PMID 27141535, 2015). "However, the relationship between KDR polymorphism in spontaneous abortion events and KDR gene expression as well as studying more KDR SNP sites should be considered in further studies." (PMID 27141535, 2015).
cervical (2 papers, 2017 to 2018). "From our analysis, DSG1, KDR, and SERPINB3 expression may have potential as robust markers that can risk-stratify cervical disease, i.e., identify cervical disease cases that have a high probability of regression, and this would be of significant clinical value." (PMID 29021401, 2017). "Statistically significant changes in KDR and SERPINB3 expression, like the known biomarker KRT17, indicate their potential in identifying high-grade cervical disease." (PMID 29021401, 2017).
Glucose intolerance (2 papers, 2018 to 2021). Glucose intolerance (GI) can be defined as dysglycemia that comprises both prediabetes and diabetes. "For example, KDR-induced severe glucose intolerance in mice may be due to high TFAs levels in fat." (PMID 33785628, 2021).
Granuloma (2 papers, 2016 to 2021). A compact, organized collection of mature mononuclear phagocytes, which may be but is not necessarily accompanied by accessory features such as necrosis. "VEGF and the endothelial cell receptor KDR (also known as VEGFR-2) are also overexpressed by granuloma cells, vascular endothelium, and the overlying epidermis in T1R." (PMID 34746168, 2021).
gynecological cancer (2 papers, 2021 to 2023). "Four, the overexpression of mRNA and KDR (kinase domain-containing receptor) protein itself has been proposed for the mechanism related to RAAS and gynecological cancer risk." (PMID 36835224, 2023).
idiopathic pulmonary arterial hypertension (2 papers, 2018 to 2023). A sporadic form of pulmonary arterial hypertension (PAH) characterized by elevated pulmonary arterial resistance leading to right heart failure. "For instance, mutations of VEGFR2/KDR were associated with a specific phenotype of idiopathic pulmonary arterial hypertension that is reminiscent of the vascular phenotype in COPD including severe PH and low DLCO." (PMID 36631133, 2023).